IL13 (interleukin 13)
Diseases named in the same sentence as IL13 in open-access papers (continued):
Sharing a sentence is not in itself a finding about the gene and the disease.
asthma (continued). "IL-13 is primarily produced by Th2 lymphocytes but also by eosinophils and NK cells and is a key mediator of asthma and allergy-related inflammation." (PMID 40191199, 2025). "All the anti–IL-5 and anti–IL-4/IL-13 therapies tested in the included studies showed beneficial effects in terms of lung function, asthma control, and reducing the rate of exacerbations." (PMID 39844912, 2025). "IL-4, IL-13, and IL-5 production has been demonstrated to induce clinical symptoms of asthma, including eosinophilia and airway hypersensitivity, indicating a clear role for ST2+ CXCR6+ Th2 cells in driving acute allergic disease." (PMID 41256356, 2025). "LCK drives T-cell receptor signaling to promote Th2 polarization and cytokine release (e.g., IL-4 and IL-13), directly exacerbating IgE-mediated allergic inflammation in diseases such as asthma and atopic dermatitis." (PMID 40649880, 2025). "In a study using an animal model of house dust mite–induced asthma, cigarette smoke was found to increase the number of eosinophils, interleukin-5 (IL-5), IL-13, and transforming growth factor-β in bronchoalveolar lavage fluid." (PMID 40443826, 2025). "In contrast, exposure to Th2-associated cytokines (e.g., IL4 or IL13) drove eosinophils polarization toward type 2 eosinophils, resulting in an increase in IL4/13 signaling and genes associated with asthma." (PMID 40025520, 2025). "IL-5 inhibitors seemed to show a more pronounced increase in asthma control than IL-4/IL-13 inhibitors with MDs of −0.4 and −0.2, respectively." (PMID 39844912, 2025). "In this regard, lunsekimig (also known as SAR443765), a bispecific nanobody-based molecule targeting both TSLP and IL-13, is being evaluated in Phase II trials for asthma." (PMID 41294800, 2025). "The data affirm the safety and efficacy of IL-4/IL-13 blockade across a broad age range, supporting dupilumab’s role as a targeted therapy for pediatric patients with T2-driven asthma." (PMID 40843371, 2025). "Lebrikizumab, another anti-IL-13 antibody, was able to improve lung function and reduce the levels of FeNO, an indicator of airway inflammation, in patients with mild asthma." (PMID 41145900, 2025). "As reported, IL-4, IL-5, and IL-13 are proinflammatory cytokines; eotaxin is a pivotal chemokine crucial for eosinophil homing to the lungs of asthma patients; and CCL4, CCL5, MCP-1, and GM-CSF recruit macrophages." (PMID 40050290, 2025). "Animal studies revealed that 4-methylpentanoic acid, generated via branched-chain amino acid metabolism, was elevated in asthma models and positively correlated with IL-5 and IL-13 expression." (PMID 41229685, 2025). "With the development of asthma, the excessive secretion of Th2 cytokines, such as IL‐4, IL‐5, and IL‐13, is considered the primary driver of immune dysregulation." (PMID 41280738, 2025). "As an important member of the Th2 cytokine family, IL-13 plays a pivotal role in the pathogenesis of asthma." (PMID 40260311, 2025). "Dupilumab is an approved therapy for severe asthma, nasal polyposis and atopic dermatitis that inhibits IL-4 and IL-13 signaling by specifically targeting the shared IL-4Rα subunit of their respective receptor complexes." (PMID 40195539, 2025). "Th2 cells secrete cytokines such as IL-4, IL-5, and IL-13, which promote IgE production and eosinophil infiltration, thereby triggering asthma symptoms." (PMID 40417314, 2025). "To establish an in vitro cell model, we treated BEAS‐2B bronchial epithelial cells with IL‐13, a well‐established asthma‐inducing cytokine." (PMID 41384344, 2025). "IL-5 and IL-13 support eosinophil survival and recruitment, and program type 2 T helper cell responses in allergy and asthma." (PMID 40821845, 2025). "It is an extracellular matrix protein upregulated in response to IL-4 and IL-13, signaling-key drivers of type 2 (T2) inflammation characterizing a major asthma endotype." (PMID 41374409, 2025).
asthma (continued). "All these immune cells release a specific set of cytokines, predominantly IL-4, IL-5, and IL-13, playing vital roles in key features of asthma pathology." (PMID 40337626, 2025). "In inflammatory diseases like asthma induced by interleukin-13 (IL-13) or allergens, miR-21 is overexpressed in monocyte and macrophage lineage cells." (PMID 39996791, 2025). "Type-2-high asthma is characterized by elevated secretion of interleukins IL-4, IL-5, and IL-13, increased eosinophil counts, and higher total immunoglobulin E (IgE) levels." (PMID 41515904, 2025). "Dupilumab, a dual IL-4 and IL-13 inhibitor, was originally developed for the treatment of severe asthma, but has been repurposed for use in chronic obstructive pulmonary disease, with preliminary reports of benefit in non-CF bronchiectasis." (PMID 39929713, 2025). "Vascular remodeling accelerated by IL-4 and IL-13 is a structural change impacting asthma and COPD pathophysiology, leading to decreased lung capacity and airflow." (PMID 40191199, 2025). "IL-13, another key cytokine in T2-high asthma, enhances goblet cell hyperplasia and mucus hypersecretion while promoting airway smooth muscle contraction and fibrosis, which contribute to airway remodeling." (PMID 40508095, 2025). "The classical asthma immune response is primarily driven by allergen-specific Th2 and type 2 innate lymphoid cells, which produce mainly IL-4, IL-5, and IL-13." (PMID 40573126, 2025). "In certain patients with severe asthma, IL-13 levels in sputum and bronchial biopsy samples stay elevated despite treatment with both inhaled and systemic corticosteroids." (PMID 40863432, 2025). "Studies have indicated that transforming growth factor beta (TGF-β) and Th2 cytokines (IL-5 and IL-13) contribute to airway remodeling as asthma progresses." (PMID 40558541, 2025). "As key cytokines of Th2-type inflammation, IL-4 and IL-13 play a crucial role in the pathogenesis of asthma." (PMID 40636260, 2025). "Dupilumab, a monoclonal antibody targeting the interleukin (IL)-4 receptor alpha subunit and IL-13, has markedly advanced the treatment of atopic conditions such as dermatitis, asthma, and chronic rhinosinusitis." (PMID 40217936, 2025). "Specifically, IL-13 reduces claudin-18 production, a crucial TJ component, decreasing transepithelial electrical resistance and increasing epithelial permeability in asthma." (PMID 41303221, 2025). "Dupilumab, the focus of this review, is a novel biologic agent that blocks IL-4 and IL-13 cytokine signaling, which is central to T2 inflammation in asthma." (PMID 40843371, 2025). "The impact of IL-13 on rhinovirus infection and innate immune and inflammatory responses to rhinovirus infection by the bronchial epithelium in asthma is poorly understood." (PMID 41427379, 2025). "In summary, these findings point to IL-13–dependent and –independent roles of MTOR signaling in the development of pathogenic epithelial changes contributing to airway obstruction in severe asthma." (PMID 40446022, 2025). "These biomarkers reflect the underlying immunopathology driven by cytokines such as interleukin-4 (IL-4), interleukin-5 (IL-5), and interleukin-13 (IL-13), which are key therapeutic targets in modern asthma management." (PMID 41149833, 2025). "IL-4 and IL-13, along with their receptors, have therefore become targets for add-on biological therapy in T2high asthma patients." (PMID 41145900, 2025). "Asthma patients with airway type 2 high inflammation (e.g., IL-13) demonstrate more eosinophils and airway hyperresponsiveness (AHR) with less interferon gamma." (PMID 40170850, 2025). "In conclusion, there were significant differences in IL-6, IL-10, IL-13, 25-(OH) D3 levels, and leptin levels among children with asthma combined with obesity/overweight and those with asthma or obesity/overweight alone." (PMID 40083433, 2025). "Our study on T2 cytokines' effects on BECs reveals that asthma BECs have an increased inflammatory response to IL-4 and IL-13." (PMID 40370530, 2025).
asthma (continued). "Although the specificity was only 50.8%, IL-13 still possesses certain clinical value in predicting poor asthma control." (PMID 40260311, 2025). "Dupilumab, a monoclonal antibody targeting interleukin-4 (IL-4) and IL-13, is widely used for the treatment of type 2 inflammatory conditions such as atopic dermatitis, asthma, and chronic rhinosinusitis with nasal polyposis." (PMID 40895907, 2025). "For instance, blocking the action of IL-4, IL-5, and IL-13 with monoclonal antibodies has shown a reduction in airway inflammation and an improvement in asthma symptoms." (PMID 40370530, 2025). "While multiple endotypes of asthma have been described, the most common is allergic asthma, characterized by the production of the type 2 cytokines IL-4, IL-5, and IL-13 following allergen exposure." (PMID 41256356, 2025). "For decades asthma has been characterized as a chronic airway condition with eosinophils in the sputum and airways, driven by IL-4, IL-5 and IL-13 from type 2 CD4+ T helper cells." (PMID 40821845, 2025). "• Critical for IgG1+ B cell conversion to IgE+ plasma cells(IL-4) and driving high-affinity IgE(IL-13) in allergic responses.• Positively correlates with disease severity in asthma and food allergy." (PMID 41181158, 2025). "Ginger improved multiple symptom-related endpoints, including Asthma Control Test (ACT) scores and asthma-specific quality of life, while modulating IL-13 and IL-17A levels." (PMID 41305557, 2025). "In allergic airway inflammation, as in asthma, IL-13 can reduce the expression of claudin-18, further impacting epithelial barrier function, as reflected in decreased claudin-18 in airway brushings from asthmatic patients." (PMID 41246133, 2025). "Inhibition of CRTh2 activation has been proposed as a treatment strategy for asthma inflammation by inhibiting the release of critical cytokines, including IL-5, IL-4, IL-13, IL-33, and IL-25, and blocking eosinophil and basophil degranulation." (PMID 40283665, 2025). "In asthma, IL-13-mediated disruption of barrier function contributes to disease persistence and severity." (PMID 41278223, 2025). "Severe asthma pathophysiology is essentially Type 2 (T2) inflammation-dominated, with the major cytokines, interleukin-4 (IL-4), IL-5, and IL-13 involved." (PMID 40283665, 2025). "These individuals with severe asthma with high BAL IL-13 and BAL neutrophilia also exhibited correlated bacterial bronchial dysbiosis involving Moraxella catarrhalis, Haemophilus sp." (PMID 39959969, 2025). "While T2 inflammation, driven by cytokines like IL-4, IL-5, and IL-13, is common in childhood asthma, non-T2 asthma, characterized by neutrophilic or pauci-granulocytic patterns, also exists." (PMID 40486460, 2025). "The Th2 subpopulation, which generates IL-4, IL-5, IL-9 and IL-13, contributes to asthma disease pathogenesis." (PMID 40095032, 2025). "IL-13 is typically considered an anti-inflammatory cytokine and is commonly involved in asthma and allergies." (PMID 39044165, 2024). "Evidence from patients with asthma and mouse models suggests that the release of IL-13 upregulates mucin gene expression in goblet cells." (PMID 38453256, 2024). "Previous studies have been successful in generating an asthma-like phenotype in vitro by differentiating airway epithelial cells cultured at the air-liquid interface (ALI) in the presence of IL-13." (PMID 38706568, 2024). "As far as IL-4Rα contributes to both IL-4 and IL-13 signaling, it is considered to be a prospective target for anti-Th2 cytokine therapy in asthma." (PMID 39767651, 2024). "The ALI lung tissue model can be transformed into an asthma model by introducing IL-13 to the medium on the basolateral side." (PMID 38732251, 2024). "The type 2 responses in asthma are regulated by various Th2 cytokines, including IL-4, IL-5, IL-9 and IL-13." (PMID 39611173, 2024).
asthma (continued). "In clinical studies, anti-TSLP Ab treatment was shown to suppress asthma exacerbation in patients with severe asthma, inhibit eosinophilic inflammation in the airway, and to decrease the concentrations of IL-5 and IL-13 in serum." (PMID 39624446, 2024). "Anti-TSLP/anti-IL-13 biologic nanobody improved lung function and small airway dysfunction in asthma beyond those reported for monovalent IL-13 or TSLP pathway targeting." (PMID 39600699, 2024). "Biologics targeting the IL-4, IL-5, and IL-13 pathways are generally effective in reducing asthma exacerbations and improving lung function." (PMID 39275297, 2024). "IL-17 treatment induces IL-19 expression, and the levels of IL-13 and -19 are closely related to the Th2 response to human asthma." (PMID 38956273, 2024). "Tozorakimab reduced biomarkers of inflammation, including serum IL-5, IL-13 and blood eosinophils, in a phase 1 study and is being evaluated in a phase 2 study in patients with asthma (ClinicalTrials.gov: NCT04570657)." (PMID 38609094, 2024). "The concentrations of IL-10, IL-13, and IL-17 A in the asthma group were significantly lower than those in the control group (IL-10: P = 0.043; IL-13: P = 0.014; IL-17 A: P = 0.026)." (PMID 38218943, 2024). "The ability of CBD-X to reduce key inflammatory markers of asthma—such as IgE, IL-4, IL-5, and IL-13—in a murine asthma model further supports its anti-inflammatory effects." (PMID 39459021, 2024). "In the IL-13-induced asthma model, the most affected pathways were found to be arginine and glutamine metabolism." (PMID 38732251, 2024). "T2-high asthma, also known as allergic asthma, is featured by hypersecretion of interleukin (IL)-4, IL-5, and IL-13, elevated eosinophil counts, and total IgE and mucus overproduction." (PMID 38168709, 2024). "In ovalbumin-sensitized mouse asthma models, exposure to wood panels of C. obtusa decreased levels of IL-4, IL-9, IL-13, and TNF-α." (PMID 38792145, 2024). "The pathophysiology of asthma is based on the elevated level of cytokines like IL-4, IL-5, and IL-13 production from Th2 cells." (PMID 39118763, 2024). "For key cytokine levels associated with asthma in the lung, TSLP/OVA administration led to significant increases of lung CCL17 and IL-13 levels in mice in G2 group relative to G1 group." (PMID 39726595, 2024). "Numerous drugs are available to treat asthma presently, including β2-adrenoceptor agonists, corticosteroids, and monoclonal antibodies targeting key cytokines (i.e., IL-5, IL-13, and IL-4)." (PMID 38340268, 2024). "To test this, we turned to a scRNAseq study in which differentiated human airway epithelial cells were treated with IL-13, a model of cytokine-induced asthma." (PMID 39294560, 2024). "This cytokine cooperates with other Th2 cytokines such as IL-4 and IL-13 and enhances the Th2 immune response commonly seen in asthma." (PMID 39407835, 2024). "On the other hand, the expression of CLCA1 was found to have a positive correlation with the levels of serum IL-13 in children diagnosed with asthma." (PMID 39176391, 2024). "Overall, it is clear that IL-13-treated ALI-cultured cells constitute a living lung model to study asthma-relevant effects." (PMID 38732251, 2024). "In this review, we discuss the possible roles of IL-4/IL-13 in the development of eosinophil-predominant severe asthma." (PMID 38785953, 2024). "The pathophysiology of asthma was strongly influenced by Th2 cytokines such as IL-4, IL-5, and IL-13." (PMID 37750936, 2024). "During this era, the roles of primary effector cells (such as mast cells and basophils) and type-2 (T2) cytokines (such as interleukin (IL)-4, IL-5 and IL-13) in asthma were identified." (PMID 39694589, 2024). "Specifically, GSEA analysis revealed GdT17 cells in asthma model were associated with various signaling pathways, including IL4/IL13 signaling, IFN-γ response and inflammatory response." (PMID 38317239, 2024).
asthma (continued). "TH2 cells are involved in the generation of cytokines that induce the different essential characteristics of asthma, including tissue eosinophilia (interleukin [IL]-5), bronchial hyperresponsiveness (IL-13), and goblet cell metaplasia (IL-4 and IL-13)." (PMID 39439788, 2024). "Th2 cells play a key role in asthma pathogenesis by secreting cytokines such as IL-4, IL-5, and IL-13, crucial for promoting allergic inflammation." (PMID 39518415, 2024). "IL-4, another Th2-dominant cytokine in asthma, sharing a promiscuous receptor with IL-13, has overlapping effects on goblet cell hyperplasia; however, IL-13 dominates over the other one." (PMID 38339210, 2024). "Th2 immune response, which induces the secretion of IL‐4, IL‐5, and IL‐13 by both innate and adaptive immune cells, is the main pathway of most parasitic immunity and immunopathological processes in asthma." (PMID 38888451, 2024). "Collectively, IL-4/IL-13 appear to play crucial roles in the development of severe eosinophil-predominant asthma." (PMID 38785953, 2024). "There is also evidence showing that tiotropium minimised the excessive release of IL-5 and IL-13 in human peripheral blood mononuclear cells derived from asthma patients." (PMID 38419021, 2024). "The specific knockout of PGI2 analogs or PGI2 receptors upregulates IL-4, IL-5, and IL-13 release from T cells in vitro and in vivo and ultimately aggravates asthma." (PMID 38297226, 2024). "Schistosoma mansoni recombinant proteins (Sm22.6 and Sm29) or antigens derived from schistosoma tegument regulate IL‐5 and IL‐13 production and enhance eosinophil production in asthma models." (PMID 38888451, 2024). "IL-13 plays a crucial role as a primary instigator of airway inflammation in asthma, as noted in a study." (PMID 39407835, 2024). "In contrast, dupilumab, a monoclonal antibody that targets the IL-4R alpha chain common to both the IL-4 and IL-13 receptors, prevents transduction signals stimulated by IL-4 and IL-13, and has been utilized for asthma treatment." (PMID 39060923, 2024). "Th2 cells play a critical role in asthma development, secreting the pro-inflammatory type 2 cytokines IL-5 and IL-13." (PMID 39459021, 2024). "These biologic agents, mainly monoclonal antibodies, are aimed at crucial molecular pathways involved in asthma’s pathogenesis, such as interleukin-5 (IL-5), interleukin-4 (IL-4), interleukin-13 (IL-13), and immunoglobulin E (IgE)." (PMID 38525773, 2024). "Asthma therapy experts have identified IL-13 as a potential therapeutic target since it plays a role in Th2 inflammation." (PMID 38699097, 2024). "Specifically, FENO -based asthma management used here measured and targeted immune activation by using an exhaled biomarker of Interleukin-13 mediated airway inflammation (exhaled nitric oxide) to assess the degree of T2 immune activation." (PMID 38691129, 2024). "Various studies have reported that IL-13–expressing ILC2s play a key role in antihelminth innate immunity, asthma, and other allergic diseases." (PMID 39405112, 2024). "Type 2 cytokines, such as IL-4 and IL-13, are known to activate the Notch pathway, which correlates with an augmented presence of goblet cells in conditions like asthma and chronic rhinosinusitis (CRS)." (PMID 38680486, 2024). "IL-13 is a cytokine secreted mainly by Th2, typically accompanying Th2 asthma, and IL-13 correlates with the severity of asthma, including eosinophilic airway inflammation, mucus secretion, airway hyperresponsiveness, and remodeling." (PMID 38218943, 2024). "In a proof-of-concept study, combined vaccination against IL-4 and IL-13 showed both prophylactic and therapeutic efficacy in a mouse model of asthma." (PMID 38609094, 2024). "HRV infection can cause the release of pro-inflammatory factor IL-25 from respiratory epithelial cells, further promoting pulmonary production of type 2 immune/inflammation effectors IL-4, IL-5, IL-13, and IgE, to exacerbate asthma allergic responses." (PMID 38780281, 2024).